EGFR (epidermal growth factor receptor)
Diseases named in the same sentence as EGFR in open-access papers (continued):
Sharing a sentence is not in itself a finding about the gene and the disease.
tumor (continued). "Tumor tissue collected at diagnosis was available only for one (ID#88) out of 3 KRAS positive patients, and its analysis confirmed the co-existence of EGFR and KRAS mutations (KRAS allelic frequency 13.8%)." (PMID 33520716, 2020). "An established tumor-intrinsic resistance mechanism is cross-talk between the EGFR and hepatocyte growth factor (HGF)/cMet pathways." (PMID 32545260, 2020). "Altogether, elimination of AMs is a better strategy to reduce EGFR mutant tumor growth and is less toxic, suggesting the selectively targeting of AMs to complement established therapies." (PMID 32125091, 2020). "miR-145 performs its tumor-suppressive role by suppression of cell proliferation through targeting epidermal growth factor receptor." (PMID 32102538, 2020). "Nb is able to mediate the endocytosis of specific receptors, such as EGFR, in tumor cells, promoting Nb as tumor-targeting ligands for drug nanocarrier designed in targeted cancer therapy and diagnosis." (PMID 33292202, 2020). "Other studies have shown that even if the EGFR signal is inhibited by monoclonal antibody drugs, other receptors on the tumor cell membrane (FGFR1, PDGFRA, or VEGFR1) can be overexpressed." (PMID 32793499, 2020). "Several studies have demonstrated that LRIG1 acts as a tumor suppressor by down-regulating ErbB and Met receptors, including EGFR." (PMID 32796636, 2020). "In this regard, Shao and colleagues found that circulating exosomes contain EGFR-VII, EGFR, PDPN and IDH1, which can be used to analyze primary tumor mutations and to indicate drug efficacy." (PMID 33396739, 2020). "In line with this, we found that EGFR‐rich EVs enhanced liver injury and shortened the overall survival of NPC transplanted mice, highlighting that EGFR‐rich EVs play an important role in determining liver‐specific tumour metastasis." (PMID 33304472, 2020). "We previously generated a tumor model exhibiting the Muv phenotype in C. elegans by introducing the human EGFR mutants EGFR L858R and EGFR T790M-L858R into the C. elegans LET-23/EGFR receptor." (PMID 33092268, 2020). "PAQR3 was demonstrated to suppress the tumor progression of NSCLC cells by modulating EGFR-regulated autophagy." (PMID 32190662, 2020). "The anti-tumor efficacy of LCD was shown through the dual inhibition of EGFR and MET activity, suggesting that it was a principal target of LCD." (PMID 32070026, 2020). "The mutations were detected in tumor tissue and matched plasma samples from 125 newly diagnosed adenocarcinoma, clinical-stage IIIB-IV patients, and compared the diagnostic values of EGFR plasma test between groups of clinical characteristics." (PMID 32746896, 2020). "This aberration has been shown to promote tumor formation and lead to the amplification of the downstream signaling of growth factor receptors, among which is Epidermal Growth Factor Receptor (EGFR)." (PMID 32069895, 2020). "Tumor-targeted polymer probes, intended for the visualization of EGFR-positive malignant tumors for successful resection via fluorescence-guided endoscopic surgery, were successfully designed, prepared and evaluated." (PMID 31906300, 2020). "Some authors found that up to 50–65% of patients with wild-type KRAS tumours were resistant to EGFR monoclonal antibodies." (PMID 33183271, 2020). "Next, we compared expression of EGFR in pre-treatment tumor biopsies to expression in 3D spheroids composed of tumor cells and CAFs (established from the same biopsy)." (PMID 33353547, 2020). "Doxycycline repression of EGFR expression in LLC tumours restored normal levels of circulating INF-β and suppressed viral titres." (PMID 33143170, 2020).
tumor (continued). "Previous mutation analysis of tumor tissue samples reported significant associations between certain clinical features among Vietnamese NSCLC patients and the prevalence of EGFR and KRAS mutations." (PMID 32850431, 2020). "We further evaluated tumor responses in a patient-derived xenograft (PDX) model with lung tumor tissue harboring EGFR L858R/T790M." (PMID 32404161, 2020). "They detected EGFRvIII in 39.5% of tumour tissue samples and in 44.7% of their paired serum exosome samples, whereas 28.1% of tumour biopsy samples had EGFR and EGFRvIII co-expression." (PMID 31666668, 2020). "ROC curves showed 75%, 75%, and 69% sensitivity and 88%, 81%, and 81% specificity for distinguishing neoplasia from normal for EGFR, claudin-1, and ErbB2, respectively." (PMID 36345439, 2020). "HR =1.89, 95%CI [1.01–3.55] (p < 0.05), and 2.42 95%CI [1.11–5.31] (p = 0.03), respectively, as compared with patients whose tumor harbored EGFR exon 19 deletion." (PMID 33272243, 2020). "The elevated colocalization of hnRNP A3 and EGFR in tumor sections was also examined by IHC double staining in a NSCLC patient." (PMID 32321917, 2020). "The association between PDGFRα overexpression in both tumor and stromal adenocarcinoma cells with RAS wild type status suggests its potential role in anti-EGFR therapy resistance and the relevance of using it as specific or adjuvant therapeutic target." (PMID 33213472, 2020). "We will also discuss how EGFR contained in EVs can be used as a non-invasive diagnostic marker of cancer, and finally, how EVs can be re-engineered to promote targeting to EGFR expressing tumours." (PMID 33143170, 2020). "We developed nanobodies binding to the mouse VEGFR2, which is overexpressed on tumor vasculature, and combined these with nanobodies specific for the cancer cell target EGFR." (PMID 32977602, 2020). "Their anti-EGFR nanobody effectively delayed tumor growth, and they later developed a biparatopic version that superiorly reduced EGFR activation, with comparable potency to its mAb counterpart, cetuximab." (PMID 32793488, 2020). "Telmisartan, an ARB, induces apoptosis of CC cells by reducing cell cycle-related proteins (G1 cyclin, cyclin D1, CDK4, and CDK6), which induces cell-cycle arrest and suppressing tumor growth of CC cells in vivo by inhibiting activation of EGFR and TIMP-1." (PMID 32708604, 2020). "The inhibitory effect on EGFR has been specifically explored and is effective in different tumor cell lines, such as EGFR-mutant non-small-cell lung cancer (NSCLC) in mice." (PMID 32532074, 2020). "The results showed a similar distribution of CAFs in the spheroids as in the tumor biopsy, as well as similar EGFR expression." (PMID 33353547, 2020). "The EGFR status in CSF ctDNA was concordant with the EGFR status of the primary tumor in 16/18 (88.9%) patients." (PMID 31944608, 2020). "We have demonstrated that tumor growth delay and in-vitro cell survival show a clear dependence between fluence rate and efficacy during EGFR targeted PDT." (PMID 31940973, 2020). "The findings suggest a higher incidence of mutant allele–specific imbalance of the KRAS, EGFR, or PIK3A mutations or presence of subclonal tumor populations harboring IDH1/2 mutations." (PMID 32333643, 2020). "We transduced two syngeneic murine HNSCC tumor cell lines to express human EGFR (MOC1- and MOC2-huEGFR) in order to facilitate evaluation of the immunologic interactions between radiation and cetuximab." (PMID 33281820, 2020). "As a receptor tyrosine kinase (RTK), EGFR is implicated in cell growth and proliferation through downstream effectors such as Ras and PI-3 kinase (PI3K) and is modulated by tumor-suppressor genes NF1 and PTEN." (PMID 33087132, 2020). "Qian and co-workers used AuNPs conjugated with single-chain variable fragment (ScFv) antibodies to target epidermal growth factor receptors (EGFR) on human cancer cells and in xenograft tumor models." (PMID 32260051, 2020).
tumor (continued). "The epidermal growth factor receptor (EGFR) family is a group of transmembrane proteins that affect tumor cell viability." (PMID 32143669, 2020). "Especially the epidermal growth factor receptor (EGFR) overexpression has been connected to a more aggressive tumor behavior." (PMID 31947591, 2020). "The overexpression of EGFR leads to aggressive tumor invasion and as such, EGFR inhibitors can effectively alleviate the malignant characteristics of many tumor cells." (PMID 32284763, 2020). "This concept has been taken even further with a Centyrin domain evolved to bind EGFR and conjugated with a fluorescent dye, which was then applied to guide surgical removal of tumour cells." (PMID 32143310, 2020). "The fold-change levels of miR-221 and EGFR at recurrence, relative to the primary tumor, were plotted on a scatter plot for each matched patient." (PMID 33082482, 2020). "Many TAAs share expression with healthy tissue (e.g. HER2, EGFR), leading to on-target/off tumor toxicities." (PMID 32206114, 2020). "We demonstrate that the EGFR–ERK axis accelerates tumor-promoting metabolic programs by mitigating SPOP-mediated ILF3 poly-ubiquitination and subsequent degradation." (PMID 31772275, 2020). "Constitutive activation of EGFR and its downstream signals results in uncontrolled alteration of gene activity and tumour proliferation." (PMID 32872665, 2020). "The treatment consists of the intravenous injection of cetuximab saratolacan, which binds to HNSCC cells with high levels of EGFR expression, followed by illumination of the tumor with NIR light (690 nm) for photodynamic therapy." (PMID 33383632, 2020). "However, the contribution of NF‐κB to EGFR‐associated tumour progression remains unclear." (PMID 32452133, 2020). "eBAT was first reported by our group as being active against human glioblastoma, a tumor with historically poor treatment prognosis and high EGFR and uPAR expression." (PMID 32630411, 2020). "The activation of EGFR plays an important role in the development and growth of tumor cells and is particularly involved in cellular responses relating to proliferation and apoptosis." (PMID 33158043, 2020). "The combination of HA and tumour-targeting antibodies (EGFR and HER2) can detect UM-SCC-22B tumour metastasis in SLNs41." (PMID 33014359, 2020). "Following the genetic test of circulating tumor DNA, all mutations disappeared, including HER2 amplification, EGFR-ZNF880 fusion, and EGFR E114K mutations." (PMID 33371069, 2020). "It is reported that patients with acquired T790M after failure of treatment with an EGFR-TKI show lower tumor PD-L1 expression levels or a lower proportion of patients with positive tumor PD-L1 expression." (PMID 33255696, 2020). "More importantly, according to our new standard, we re-classify the complex evolving tumor cell resistance mechanisms, including those involving exosomes, non-coding RNA and the tumor microenvironment, against EGFR monoclonal antibodies." (PMID 32793499, 2020). "It is highly selective to MET and has a high inhibition potency, being up to 30 times more potent than Crizotinib, and recedes the EGFR TKI resistance in tumor cells." (PMID 33153004, 2020). "In support of this notion we observed acquisition of tumor-specific SEs in proximity to known oncogenes such as EGFR and MYC, as well as a large number of genes whose role in TNBC has not yet been established." (PMID 32584896, 2020). "Here, we comprehensively review the newly identified biological properties and anti-tumor mechanisms of EGFR monoclonal antibodies." (PMID 32793499, 2020). "One of the aims for analyzing the EGFR and fibronectin expression was to study the growth pattern of tumor cells and CAFs in spheroids and to confirm the presence of CAFs." (PMID 33353547, 2020). "Despite high initial response and disease control rate, virtually all patients receiving these EGFR TKIs eventually experience tumor progression due to the emergence of drug resistance." (PMID 32397295, 2020).
tumor (continued). "Confusion matrix of combined biomarker panel using circulating tumor cell and EGFR in the discovery phase." (PMID 32080083, 2020). "In addition, the transformation of tumor tissue types, epithelial mesenchymal change, epigenetic changes, and abnormal microenvironment of tumor cells may cause resistance to EGFR‐TKIs; the mechanisms for approximately 18%–20% of cases with acquired resistance remain unknown." (PMID 32163227, 2020). "The characterization of PDXs also included sequence analysis of tumor PDXs for mutations in PI3KCA (exons 9 and 20) and EGFR (exons 18, 19, 20, and 21)." (PMID 32414394, 2020). "This dependency of EGFR on TMEM16A was also observed in HNSCC, wherein inhibitors of TMEM16A synergized with EGFR inhibitors to limit tumor growth." (PMID 32575848, 2020). "YTHDF2 directly binds to the m6A modification site of EGFR 3′-UTR, promotes the degradation of EGFR mRNA, and inhibits the proliferation of cancer cells and tumor growth." (PMID 33552994, 2020). "In the pre-EGFR-TKI-treated tumor samples, pIGF-1R expression was evaluated using IHC staining and scored as very high (3+), high (2+), low (1+), and no expression of pIGF-1R." (PMID 32929081, 2020). "Although EGFR is mutated in a large fraction of NSCLC, and it acts as an established tumor driver, under pharmacological stress this driver seems to be replaced by an alliance comprising, in addition to EGFR, also HER2 and HER3." (PMID 32847130, 2020). "HAB21 was expressed as either a human IgG1, IgG4, IgG2Δa, or IgG1FcDead subclass and macrophage phagocytosis of DLD-1 tumor cells opsonized with the anti-EGFR antibody cetuximab alone or in combination with hAB21 was quantified by flow cytometry." (PMID 33256806, 2020). "Consistent with experimental findings, simulations with the model also suggested that the higher-EGFR PANC-1 tumour would continue to progress under either regimen." (PMID 32913288, 2020). "Inhibited JAK1,2/STAT3 signalling pathway activation was also confirmed in EGFR-TKI-treated NSCLC tumour tissues." (PMID 31892990, 2020). "The canonical EGFR pathway is one of the most studied cellular signalling pathways in the context of tumour progression and targeted drug development." (PMID 33143170, 2020). "The effects of this new paradigm in EV EGFR signalling in cancer are now evolving, and it is beginning to provide new insights into tumour microenvironment (TME) communication and cancer progression." (PMID 33143170, 2020). "The activation of the EGFR/Ras-signalling pathway in tumour cells induces a distinct chemokine repertoire, which in turn modulates the tumour microenvironment." (PMID 32601464, 2020). "There have been in vivo studies of synergistic antitumor effects with chimeric toxins, that is, saporin-EGF and saponin for epidermal growth factor receptor expressing tumor xenografts." (PMID 32256588, 2020). "Cetuximab, which is an anti-EGFR mAb, induces apoptosis in tumor cells by blocking ligand binding and receptor dimerization." (PMID 32698317, 2020). "Hippo pathway (red) components were prominent among the genes identified as cooperating with EGFR to drive tumor formation." (PMID 32737065, 2020). "EGFR-TKI led to increased PD-L1 expression from 14% at baseline to 28% of patients, accompanied by higher tumour mutational burden, a measure of how many mutations per megabase of genome the tumour has managed to accumulate." (PMID 33302515, 2020). "EGFR, in particular EGFRVIII, is rarely expressed in healthy tissues, characterizing this exclusive tumor-mutated receptor as an attractive therapeutic molecule." (PMID 32391048, 2020). "The colocalization of EGFR and hnRNP A3 was clearly much higher in the tumor sections than the hyperplasia sections." (PMID 32321917, 2020). "Among the 33 patients for whom RAS status of the primary tumor was available, 16 patients received chemotherapy plus antiangiogenic drugs while 17 received chemotherapy plus epidermal growth factor receptor (EGFR) inhibitors." (PMID 33227095, 2020).
tumor (continued). "Pharmacological inhibition of FASN by orlistat (Xenical) (an FDA-approved anti-obesity drug) inhibits EGFR palmitoylation, limiting tumor cell survival." (PMID 32516941, 2020). "In the clinic, the T790M mutation is already present (at very low percentages) in the majority of the tumours before undergoing anti-EGFR treatment." (PMID 32572029, 2020). "Tumor cells in EGFR overexpression were more prone to prolidase, which resulted in inhibition of EGFR phosphorylation and downstream proteins such as Akt and ERK1/2, as well as STAT3 signaling." (PMID 32824561, 2020). "Another study proved that the combination treatment of EGFR-TKIs and MDM2 inhibitors can inhibit the proliferation of tumor cells and enhance the anti-tumor effect of EGFR-TKIs." (PMID 32611363, 2020). "Tumor stage and TNM status between the groups were similar, whereas the mutated EGFR group had a significantly higher rate of clear cell differentiation (12.0% vs. 7.6%, p = 0.005)." (PMID 33050100, 2020). "Studies in primary tumor cells with USP8 mutants have shown that gefitinib treatment (EGFR inhibitor) can reduce ACTH secretion." (PMID 33537004, 2020). "Downregulation of hnRNP A3 reduced the nuclear accumulation of EGFR, and this was accompanied by reduced tumor growth ability in vitro and in vivo." (PMID 32321917, 2020). "In summary, we applied NGS in NSCLC tumor tissue at the moment of diagnosis and in liquid biopsy at the moment of progression in a subset of EGFR mutant patients." (PMID 32047821, 2020). "Here, we review the clinical results of immune checkpoint inhibitors in EGFR-mutant NSCLC, focusing on the dynamic immune composition of EGFR-mutant tumor microenvironment." (PMID 32760402, 2020). "Future in vivo experiments using tumour xenografts with varying sensitivities to EGFR inhibition, will hopefully elucidate the local complement response to EGFR inhibitors in the tumour microenvironment." (PMID 32054454, 2020). "Studies on the transport of EGFR by tumor derived EVs revealed that the transported EGFR will localize in the membrane of the recipient cells, thus preparing distant sites for metastasis." (PMID 32886718, 2020). "Patients with EGFR mutant tumor also exhibited shorter PFS, with borderline significance (HR 2.00; 95% CI, 0.98 - 4.06; P = 0.056)." (PMID 33552993, 2020). "As a proof of principle study, nanobody-targeted PDT was applied on an oral squamous cell carcinoma orthotopic mouse tumor model overexpressing EGFR." (PMID 32977602, 2020). "The concordance rate between the EGFR plasma and the EGFR tumor tests was determined by the Kappa statistic." (PMID 32746896, 2020). "Other potential therapeutic targets to combat GBM chemoresistance include the phosphoinositide 3-kinase pathway, nuclear factor-κB, the hepatocyte/scatter factor (c-MET), the epidermal growth factor receptor, and the tumor microenvironment." (PMID 35582224, 2020). "Most of the baseline clinical characteristics including age, sex, ECOG PS, histology, EGFR and ALK mutation status, PD‐L1 tumor proportion score, CRT protocol and timing of durvalumab initiation were similar between the high and low NLR groups." (PMID 32281272, 2020). "For these cell lines activation of EGFR leads to inhibition of the tumor cell proliferation, whereas for other types of tumor cells, such as MCF-7, activation of EGFR, on the contrary, leads to the induction of cell growth." (PMID 32194412, 2020). "These screens have identified an expanded genomic repertoire of potential tumor suppressors that cooperate with EGFR or Yki." (PMID 32737065, 2020). "Increased expression of EGFR was observed in tumor cells cultured with CAFs, which correlated with increased positive Ki67 cells." (PMID 33353547, 2020).